TSKU (tsukushi, small leucine rich proteoglycan)
Description:
Contributes to various developmental events and other processes such as wound healing and cholesterol homeostasis through its interactions with multiple signaling pathways. Wnt signaling inhibitor which competes with WNT2B for binding to Wnt receptor FZD4 and represses WNT2B-dependent development of the peripheral eye. Plays a role in regulating the hair cycle by controlling TGFB1 signaling. Required for the development of the anterior commissure in the brain by inhibiting neurite outgrowth. Essential for terminal differentiation of hippocampal neural stem cells. Plays a role in regulating bone elongation and bone mass by modulating growth plate chondrocyte function and overall body size. Required for development of the inner ear through its involvement in stereocilia formation in inner hair cells. Facilitates wound healing by inhibiting secretion of TGFB1 from macrophages which prevents myofibroblast differentiation, maintaining inflammatory cell quiescence. Plays a role in cholesterol homeostasis by reducing circulating high-density lipoprotein cholesterol, lowering cholesterol efflux capacity and decreasing cholesterol-to-bile acid conversion in the liver. In one study, shown to negatively regulate sympathetic innervation in brown fat, leading to reduced energy expenditure. In another study, shown not to affect brown fat thermogenic capacity, body weight gain or glucose homeostasis.
Synonyms: E2IG4; LRRC54; TSK
Tractability: Antibody: UniProt places it where antibodies can reach, with medium confidence; UniProt predicts a signal peptide or a membrane-spanning region; its Gene Ontology location is reachable by antibodies, with medium confidence. PROTAC: its protein half-life has been measured.
Gene: Protein-coding gene on chromosome 11 (76,781,403 to 76,798,157, forward strand). Ensembl gene ENSG00000182704.
Subcellular location: Secreted
Subcellular location (Human Protein Atlas): Nucleoplasm; Nuclear bodies; Predicted to be secreted
Gene Ontology:
Molecular function: transforming growth factor beta binding
Biological process: anterior commissure morphogenesis; bone growth; camera-type eye development; cholesterol efflux; cholesterol homeostasis; cholesterol metabolic process; ciliary body morphogenesis; energy homeostasis; growth plate cartilage chondrocyte development; hippocampus development; inner ear receptor cell stereocilium organization; negative regulation of myofibroblast differentiation; negative regulation of neuron projection development; negative regulation of transforming growth factor beta1 production; negative regulation of Wnt signaling pathway; positive regulation of hair cycle; regulation of gene expression; wound healing
Cellular component: extracellular region; gel phase of interstitial matrix
Genetic constraint (gnomAD): Loss-of-function variants: 6 observed, 12.98 expected, observed/expected ratio (o/e) 0.46, 90% interval 0.25 to 0.91. The upper end of that interval is the gene's LOEUF score, 0.91, which puts it in group 3 of 6, group 1 being the genes least tolerant of losing a copy. Missense variants: 407 observed, 480.94 expected, observed/expected ratio (o/e) 0.85, 90% interval 0.78 to 0.92. Synonymous variants: 220 observed, 236.04 expected, observed/expected ratio (o/e) 0.93, 90% interval 0.83 to 1.04.
Homologues: Orthologues: chimpanzee TSKU (98% identical), macaque TSKU (97% identical), pig TSKU (88% identical), dog TSKU (87% identical), guinea pig TSKU (87% identical), mouse Tsku (84% identical), rabbit TSKU (84% identical), rat Tsku (84% identical), tropical clawed frog tsku (48% identical), zebrafish tsku (46% identical). Paralogues in human: IGFALS (28% identical), TLR8 (23% identical), TLR3 (23% identical), TLR7 (23% identical), LRRC32 (22% identical), NRROS (21% identical), TLR5 (20% identical), CD180 (17% identical), TLR1 (15% identical), TLR6 (15% identical), RXFP2 (15% identical), TLR10 (15% identical), and 10 more.
Diseases named in the same sentence as TSKU in open-access papers:
TSKU is named in the same sentence as 39 diseases in open-access papers, as found by Europe PMC text mining. Sharing a sentence is not in itself a finding about the gene and the disease. The quoted sentences say what the papers report.
Obesity (5 papers, 2020 to 2025). Accumulation of substantial excess body fat. "Emerging genetic targets include the TSKU gene rs11236956-G allele, which has been linked to obesity-related metabolic disorders." (PMID 41340654, 2025). "To determine the association between TSK and metabolic traits, we performed microarray analysis to explore TSKU-related SNPs in the obesity group, which attenuated the confounding effect of BMI." (PMID 33860453, 2021). "Thus, we screened the TSKU gene region and identified rs11236956 as a novel variant associated with serum TSK level in subjects with obesity." (PMID 33860453, 2021).
neuroblastoma (4 papers, 2018 to 2025). Neuroblastoma (NB) is the most common solid, extracranial childhood tumor. "In our study, we found that depletion of TSKU in neuroblastoma cells induced cell differentiation and reduced cell viability, supporting its potential oncogenic function." (PMID 30550571, 2018). "As above, the neuroblastoma patients were classified by tumor TSKU mRNA levels into high or low groups in the each dataset." (PMID 30550571, 2018). "This supports the potential clinical relevance of miR-2110-mediated down-regulation of TSKU expression in neuroblastoma tumorigenesis." (PMID 30550571, 2018). "In this study, we demonstrated that miR-2110 functioned as a generic repressor of neuroblastoma cell survival and growth and identified TSKU as the direct target of miR-2110 that play the major role in mediating such function." (PMID 30550571, 2018). "In order to evaluate the clinical relevance of miR-2110-mediated down-regulation of TSKU in neuroblastoma patients, we examined tumor miR-2110 and TSKU mRNA levels in neuroblastoma patients as well as their correlation with patient survival based on the published SEQC neuroblastoma patient dataset." (PMID 30550571, 2018). "Whether such functions of TSKU is also cell-type specific and only limited to neuroblastoma certainly warrants further investigation." (PMID 30550571, 2018). "In neuroblastoma and non-small cell lung cancer (NSCLC), high expression of TSKU was negatively correlated with patients’ prognosis." (PMID 36118855, 2022). "The absence of TSKU increases cleaved poly ADP-ribose polymerase (PARP) protein levels and caspase 3/7 activity thereby increasing carcinogenicity in neuroblastoma cells." (PMID 40186177, 2025).
lung carcinoma (3 papers, 2021 to 2025). "The analysis of a cohort (GSE31210, N=204) of lung cancer patients demonstrated that high TSKU expression was strongly associated with poor overall survival (P =1.90E-05)." (PMID 33428594, 2021). "This study will support us to explore the association between TSKU expression and the prognosis of lung cancer patients based on public databases." (PMID 33428594, 2021). "Among the 14 types of combination meta-analysis, we found that high TSKU expression was significantly associated with poorer OS in lung cancer and poorer DFS in colorectal cancer." (PMID 33428594, 2021). "Further, TSKU expression is strongly associated with poor overall survival in lung cancer." (PMID 40186177, 2025). "High TSKU expression was strongly associated with poor overall survival of patients with lung cancer by multivariate Cox regression analysis, with HROS of 4.700 (95 % CI 2.360–9.360, P =1.10E-05) and HRRFS of 3.400 (95 % CI 2.030–5.810, P =4.00E-06), respectively." (PMID 33428594, 2021). "The previous study also confirmed that TSKU is more highly expressed in their lung cancer tissue (N=62) and cells and activates proliferation in cancer cells." (PMID 33428594, 2021). "These two databases revealed that TSKU expression has an impact on the prognosis of some cancers, including lung cancer (LUAD)." (PMID 33428594, 2021). "According to TSKU methylation levels, we further analyzed TSKU hypomethylation levels in cancer tissue and found a low proportion of B cells in lung cancer patients." (PMID 33428594, 2021). "These two databases showed consistent results in the differential TSKU expression between tumor and normal tissues in the lung cancer (LUAD and LUSC), BRCA, KICH, KIRC, and LIHC datasets." (PMID 33428594, 2021). "In addition, the cohort (jacob-00182-HLM, N=79) of lung cancer patients with the high TSKU expression also showed poorer OS than those with low TSKU expression (P=0.029)." (PMID 33428594, 2021). "In addition, we found only research on the functional mechanism of TSKU expression in lung cancer." (PMID 33428594, 2021).
Hydrocephalus (2 papers, 2022). Hydrocephalus is an active distension of the ventricular system of the brain resulting from inadequate passage of CSF from its point of production within the cerebral ventricles to its point of absorption into the systemic circulation. "Some patients with hydrocephalus have an exonic mutation in the TSKU gene." (PMID 36478736, 2022).
non-alcoholic fatty liver disease (2 papers, 2022 to 2025). "A recent study identified TSKU protein as a potential blood biomarker for non-alcoholic fatty liver disease." (PMID 40618567, 2025).
B-cell non-Hodgkin lymphoma (1 paper, 2022). The most common type of non-Hodgkin lymphoma. "Interestingly, a subset of the members in the SLRP protein family have been previously identified in B-cell Non-Hodgkin’s lymphomas including DCN, BGN, ASPN, FMOD, LUM, PRELP, and TSKU." (PMID 36873459, 2022).
liver cancer (1 paper, 2021). An epithelial or non-epithelial malignant neoplasm that arises from the liver. "Lower expression of TSKU in tumors than in normal tissues was observed in breast, kidney, and liver cancers and sarcoma." (PMID 33428594, 2021).
uterine corpus endometrial carcinoma (1 paper, 2021). A endometrial carcinoma (disease) that involves the body of uterus. "We found that low TSKU methylation was associated with poor prognosis in ACC, BRCA, KICH, LGG (brain lower grade glioma), and PAAD, while high TSKU methylation was associated with good prognosis in KIRC and UCEC (uterine corpus endometrial carcinoma)." (PMID 33428594, 2021).
tumor (6 papers, 2018 to 2025). "Despite the possible functional potential of TSKU in cancer, little is known about whether TSKU is associated with clinical prognosis and tumor-infiltrating immune cells (TIICs) in human cancer." (PMID 33428594, 2021). "Our study provides insights into the potential role of TSKU in tumor immunology and its identification as a prognostic biomarker." (PMID 33428594, 2021). "To further validate the differential TSKU expression between different tumor and normal tissues, we analyzed TCGA (The Cancer Genome Atlas) data via the TIMER (Tumor Immune Estimation Resource) database." (PMID 33428594, 2021). "In this study, we found for the first time that the levels of TSKU methylation and expression significantly correlated with tumor-infiltrating B cell levels in NSCLC." (PMID 33428594, 2021). "Given the role of TSKU in regulating the expression of cytokines involved in immunoregulation in the wound healing process, we hypothesized that TSKU may be involved in the tumor immune response and have effects on prognosis in NSCLC." (PMID 33428594, 2021). "We also evaluated the correlation of TSKU expression with TIIC levels in diverse tumor types." (PMID 33428594, 2021). "For instance, studies have documented a strong inverse association between miR-2110 (low tumor levels) and its target, TSKU (high tumor mRNA levels), and further demonstrated a significant correlation of both low miR-2110 and high TSKU mRNA with poor patient survival." (PMID 31867575, 2019). "TSKU might be a potential prognostic biomarker involved in tumor immune infiltration in NSCLC." (PMID 33428594, 2021). "In addition, high TSKU expression combined with low tumor-infiltrating B cell levels may influence the prognosis of patients with NSCLC." (PMID 33428594, 2021). "Moreover, we also observed correlations between TSKU expression and gene markers of B cells and DCs, which demonstrated that TSKU expression might play a role in regulating tumor immunity in both LUAD and LUSC." (PMID 33428594, 2021).
cancer (5 papers, 2018 to 2024). A tumor composed of atypical neoplastic, often pleomorphic cells that invade other tissues. "TSKU expression has been significantly associated with the prognosis in some kinds of cancers, including lung, head and neck, breast, and soft tissue cancers." (PMID 33428594, 2021). "In light of the significant negative correlation between differential methylation and expression, we further analyzed the association between methylation level of TSKU and overall survival in 24 types of cancer from TCGA data via the MethSurv database." (PMID 33428594, 2021). "Based on the analysis of the Oncomine database, TSKU expression was higher in lung, bladder, brain and CNS, and other cancers than in normal tissues." (PMID 33428594, 2021). "We evaluated the impact of TSKU expression on the prognosis of various cancers using PrognoScan." (PMID 33428594, 2021). "However, there have been few reports on exploring the functional significance of TSKU in human cancers." (PMID 33428594, 2021). "Similar to TSKU, decorin (DCN) and biglycan (BGN) are two key SLRPs that have altered expression in various cancers with diverse clinical outcomes, and BGN serves as a potential marker of cancer proliferation associated with poor clinical outcome." (PMID 33428594, 2021). "The function of TSKU in cancers has not been exploited prior to our study." (PMID 30550571, 2018).
renal disease (1 paper, 2021). "Expression of TSKU has been implicated in renal disease through fibrosis and inflammation." (PMID 34285226, 2021).
TSKU also shares sentences with these, for which no sentence is quoted: metabolic disease (5 papers); infection (4); acute liver failure (3); liver steatosis (3); dyslipidemia (2); hyperthyroidism (2); Insulin resistance (2); non-small cell lung carcinoma (2); steatosis (2); systemic sclerosis (2); atherosclerosis (1); breast invasive carcinoma (1); cardiovascular diseases (1); cholangiocarcinoma (1); colon adenocarcinoma (1); colorectal cancer (1); COVID-19 (1); hearing loss (1); Hyperinsulinemia (1); kidney chromophobe (1); liver dysfunction (1); lung adenocarcinoma (1); lung squamous cell carcinoma (1); neurodegenerative disease (1); non-alcoholic steatohepatitis (1); rectum adenocarcinoma (1); sarcoma (1); stomach adenocarcinoma (1).